KIAA1191 (KIAA1191)
Description:
Potential NADPH-dependent oxidoreductase. May be involved in the regulation of neuronal survival, differentiation and axonal outgrowth.
Synonyms: P33MONOX; FLJ21022; p60MONOX
Tractability: PROTAC: ubiquitination databases record sites on it; its protein half-life has been measured.
Gene: Protein-coding gene on chromosome 5 (176,339,650 to 176,366,459, reverse strand). Ensembl gene ENSG00000122203.
Subcellular location: Cytoplasm
Subcellular location (Human Protein Atlas): Nucleoplasm
Gene Ontology:
Molecular function: protein binding
Cellular component: mitochondrion; cytoplasm
Genetic constraint (gnomAD): Loss-of-function variants: 23 observed, 34.97 expected, observed/expected ratio (o/e) 0.66, 90% interval 0.47 to 0.93. The upper end of that interval is the gene's LOEUF score, 0.93, which puts it in group 3 of 6, group 1 being the genes least tolerant of losing a copy. Missense variants: 313 observed, 389.98 expected, observed/expected ratio (o/e) 0.8, 90% interval 0.73 to 0.88. Synonymous variants: 126 observed, 146.23 expected, observed/expected ratio (o/e) 0.86, 90% interval 0.75 to 1.
Homologues: Orthologues: chimpanzee KIAA1191 (99% identical), macaque KIAA1191 (96% identical), dog KIAA1191 (88% identical), pig KIAA1191 (85% identical), guinea pig KIAA1191 (81% identical), mouse 4833439L19Rik (80% identical), rat Kiaa1191 (80% identical), rabbit KIAA1191 (68% identical), zebrafish zgc:123105 (55% identical).
Diseases named in the same sentence as KIAA1191 in open-access papers:
KIAA1191 is named in the same sentence as 1 disease in open-access papers, as found by Europe PMC text mining. Sharing a sentence is not in itself a finding about the gene and the disease. The quoted sentences say what the papers report.
tumor (1 paper, 2023). "In tumor tissues, the staining intensity of the target genes was strong (BID, HPRT1, SMN1), high (PGAM5), or medium (FADD, KIAA1191)." (PMID 37760507, 2023).